INS (insulin)
Diseases named in the same sentence as INS in open-access papers (continued):
Sharing a sentence is not in itself a finding about the gene and the disease.
digestive system cancer (7 papers, 2018 to 2025). A primary or metastatic malignant neoplasm involving any part of the digestive system. "Our findings are compatible with a model linking modifiable factors (adiposity, physical activity, dietary pattern) with insulin, or closely related metabolic factors, and risk of digestive system cancers." (PMID 30740588, 2018). "As proposed in our study, changes in insulin resistance may influence the risk of digestive system cancers by altering body shape phenotypes." (PMID 41064293, 2025). "In conclusion, our analysis within two large prospective cohorts of men and women showed that higher scores of two indices assessing the insulin secretion potential of dietary and lifestyle behaviors are associated with higher risk of developing digestive system cancers." (PMID 30740588, 2018). "We speculate that these results are because of the close mechanistic links between insulin resistance and digestive system cancer." (PMID 41064293, 2025). "However, the dynamic changes in insulin resistance and how they influence body shape phenotype, leading to digestive system cancers, remain unknown to us." (PMID 41064293, 2025).
bone disorder (6 papers, 2011 to 2026). "Therefore, to understand T2DM associated bone disorders and the underlying mechanisms, we investigated the effect of glucose and insulin on the physiological functions of BMSCs." (PMID 32017705, 2020). "The amelioration of osteopathy by early-started sufficient insulin treatment in our study was in accord with the bone-anabolic role of insulin 1 and efficacy of insulin therapy for bone disease in T1DM in clinical 1, 47 and preclinical 48, 49 studies." (PMID 33664862, 2021). "Our results demonstrated that insulin-TGF-β1 pathway impeded osteogenesis of BMSCs by inhibiting autophagy and promoting premature senescence, indicating a previously unknown mechanistic linkage of insulin-TGF-β receptor II (TβRII) pathway in T2DM associated bone disorders." (PMID 32017705, 2020). "Additionally, osteopathy defects, which are serious complications of T1DM and T2DM, result from interruption of insulin and IGF1R." (PMID 38274107, 2023).
Intestinal Diseases (6 papers, 2022 to 2025). "The purpose of this review is to summarize the application and treatment of CANPs in intestinal diseases and insulin delivery." (PMID 35384787, 2022). "The purpose of this review is to introduce the preparation methods and related properties of CANPs, and summarize their recent application on insulin delivery and intestinal diseases, e.g. colorectal cancer (CRC) and ulcerative colitis (UC)." (PMID 35384787, 2022).
adenocarcinoma (5 papers, 2015 to 2026). A common cancer characterized by the presence of malignant glandular cells. "We have now tested this possible implication of Sam68 in leptin and insulin signalling in adenocarcinoma cells by studying Tyr-phosphorylation mediated by these hormones." (PMID 27415018, 2016). "To check the effect of Sam68 down-regulation on insulin and leptin-dependent phosphorylation of the main proteins of these signalling pathways, we used adenocarcinoma MCF7 cells as it was shown to have better response to insulin and leptin." (PMID 27415018, 2016). "INS, TOP2A, ACACA, ALB, and TXN are the key genes which play an important role in adenocarcinoma." (PMID 30425814, 2018). "In order to check the effect of leptin and insulin on Sam68 expression in the three adenocarcinoma cell lines, they were independently incubated in the absence of serum with and without leptin or insulin (1 nM) for 24 h." (PMID 27415018, 2016).
central nervous system diseases (5 papers, 2012 to 2024). "It is associated with insulin sensitivity and with anti-inflammatory, angiogenic, and vasodilator properties, which can have an influence on central nervous system disorders." (PMID 35053667, 2022). "Collectively, emerging studies are revealing that insulin signaling pathways are active contributors to sensory nerve modulation, and this review highlights this novel activity and should provide new insight into insulin's role in both peripheral and central nervous system diseases." (PMID 28066166, 2016). "Therefore, with regard to the limited studies investigating the therapeutic effects of insulin in reducing CIPNM in children and also to prevent acquired paresis unrelated to the central nervous system diseases, this study assessed the important role of insulin therapy in CIPNM." (PMID 24665266, 2012).
hematologic diseases (5 papers, 2013 to 2025). "Though the best treatment for the Warburg effect in hematological malignancy is not yet known, commonly used modalities for treatment include chemotherapy, bicarbonate infusion, renal replacement therapy, and insulin infusion." (PMID 38916019, 2024). "CAPN10 plays important roles in the translocation of glucose transporter 4 (GLUT4), secretion of insulin and apoptotic processes in pancreatic cells, while TSPAN8 has been described as a prognostic indicator for patients with certain solid tumors, but not for hematological malignancies." (PMID 34502231, 2021).
movement disorder (5 papers, 2014 to 2025). Neurological conditions resulting in abnormal voluntary or involuntary movement, which may impact the speed, fluency, quality and ease of movement. "When the acute symptoms of seizures and movement disorders relieved within a mean of 2 ± 1 day (1-4 days), intravenous insulin was withdrawn and insulin was injected subcutaneously every 4 h." (PMID 25422738, 2014). "The effect of long-term insulin use on movement disorders in PD has not been studied." (PMID 38229119, 2024).
musculoskeletal disorders (5 papers, 2013 to 2025). "CAD-genes from the nutritional and metabolic class are related to response to insulin stimulus and positive regulation of lipid process, while CAD-genes for musculoskeletal diseases only show an association with the extracellular region." (PMID 28175300, 2016).
benign tumors (4 papers, 2014 to 2024). "While they are primarily benign, malignant cases are observed, as we have largely associated with elevated insulin and proinsulin levels along with a size larger than that of benign tumors." (PMID 39735090, 2024). "Compared to benign tumors, malignant insulinomas tended to be larger, be associated with higher plasma insulin concentrations and to be associated with metastases." (PMID 37194422, 2023). "The results of the present study suggest that strict maintenance of intraoperative normoglycemia, using intravenous insulin and glucose (GIN), contributes to prevent the impairment of both short and long-term memory function after open heart surgery." (PMID 24941010, 2014).
skeletal dysplasia (4 papers, 2014 to 2021). Any Mendelian diseases that affects growth and development of the skeleton. "All previous studies could not conclude whether the development of AN in ACH/HCH is due to reduced insulin sensitivity secondary to the skeletal dysplasia or GH treatment." (PMID 25505998, 2014). "Our findings suggest that it might be due to insulin insensitivity either related to skeletal dysplasia itself or secondary to treatment with recombinant human GH or may represent a new association that should be established by further studies." (PMID 25505998, 2014).
connective tissue disease (3 papers, 2010 to 2023). "The most frequent type of adverse events in the NPH insulin group was musculoskeletal and connective tissue disorders (three patients reporting four events) and in the insulin GLA group was infections (two patients reporting one event each)." (PMID 20415692, 2010).
electrolyte imbalance (2 papers, 2021 to 2024). "The mainstay of treatment remains rehydration, early insulin initiation, identification and treatment of precipitants, and management of electrolyte imbalance." (PMID 39060948, 2024).
hematologic cancer (2 papers, 2023 to 2025). "Across all hematologic cancers, GLP-1RA use was associated with 54% lower risk compared with insulin." (PMID 40048168, 2025). "This study aims to compare the risks of hematologic cancers in patients with T2D treated with GLP-1RA compared with metformin and insulin." (PMID 40048168, 2025).
skeletal muscle disorder (2 papers, 2022 to 2025). A disease involving the skeletal muscle tissue. "Skeletal muscle utilizes approximately 80% of available glucose in the body, and skeletal muscle disorders can thus contribute to abnormal glucose homeostasis and insulin sensitivity." (PMID 40629651, 2025).
hepatobiliary disorder (1 paper, 2025). A non-neoplastic or neoplastic disorder that affects the liver, bile ducts, and gallbladder. "Notably, ceritinib and alectinib both showed elevated hepatobiliary disorder signals, likely attributable to ceritinib’s dual inhibition of insulin and IGF-1 receptors, which can disrupt hepatic metabolic homeostasis." (PMID 40137538, 2025).
INS also shares sentences with these, for which no sentence is quoted: acute myocardial infarction (76 papers); cardiac arrhythmia (36); thyroid (31); Coma (23); Parkinson’s (17); maturity-onset diabetes of the young (15); unstable angina (15); hypertrophy (14); gastrinoma (12); portal hypertension (12); diabetic polyneuropathy (11); Overweight (11); amoebiasis (9); pulmonary hypertension (9); non-Hodgkin lymphoma (8); Polyphagia (8); carcinoids (7); optic atrophy (7); Peptic ulcer (7); placental abruption (7); cellulitis (6); gangrene (6); medullary thyroid carcinoma (6); Multiple Organ Failure (6); orthostatic hypotension (6); sickle cell disease (6); Ventricular hypertrophy (6); atopic dermatitis (5); autoimmune hepatitis (5); cocaine addiction (5).
A further 566 diseases each share a sentence with INS in 5 papers or fewer.